IRF2 (interferon regulatory factor 2)
Diseases named in the same sentence as IRF2 in open-access papers (continued):
Sharing a sentence is not in itself a finding about the gene and the disease.
melanoma (continued). "Since melanomas are one of the cancers that can be immunogenic and a target of CD8 T cells, we further analyzed the functional consequences of IRF2 loss in these cancers." (PMID 39281881, 2024). "The IRF2 gene-edited melanomas had reduced expression of transcripts for genes in the MHC I pathway and decreased levels of MHC I complexes on the cell surface." (PMID 39281881, 2024). "Intriguingly, our RNA-seq data reveals substantial upregulation of IRF2 expression in Mll4−/− melanoma cells." (PMID 36323669, 2022). "Knockdown of E4F1 resulted in an increase in CASP8 levels while IRF2 knockdown results in reduction of CASP8 RNA levels in melanoma, breast cancer, and melanocytes, consistent with respective roles for E4F1 and IRF2 as a potential repressor and activator in cells of melanocytic lineage." (PMID 41542517, 2026). "The effect of IRF2 on B16 melanoma growth in immunocompetent vs immunodeficient mice." (PMID 39281881, 2024). "Loss of IRF2 reduces the expression of MHC I pathway components in human and mouse melanomas." (PMID 39281881, 2024). "Downregulation of IRF2 in human melanomas might be creating a double whammy via downregulation of MHC I antigen presentation to escape immune detection and releasing the brakes on cell proliferation at the same time." (PMID 39281881, 2024). "Effect of IRF2 loss on growth and response to CPI therapy in a primary human melanoma." (PMID 39281881, 2024). "Importantly we found that type I and II IFN stimulation of IRF2-null melanomas restored their MHC I pathway and MHC I molecule expression and that this was in part dependent on IRF1." (PMID 39281881, 2024). "Indeed, gene expression correlation analyses suggest, for example, that E4F1 may play a prominent role for CASP8 regulation in melanocytes, while the activator IRF2 may play a larger role in regulation of CASP8 in melanomas." (PMID 41542517, 2026). "In melanomas that were deficient in both IRF1 + IRF2, IFN treatment failed to restore the MHC I pathway and reverse the resistance to CPI, indicating that the beneficial effects of the IFN treatment were mediated through the substitutive activity of the transcription factor IRF1." (PMID 39281881, 2024). "We were able to replicate this positive correlation specifically between IRF2 and CASP8 in independent panels of melanoma cell lines (P = 4.23 × 10−4, r = 0.38) and the Leeds Melanoma Cohort (P = 8.74 × 10−4, r = 0.30)." (PMID 41542517, 2026). "In vivo studies showed that the overexpression of IRF-2 resulted in larger tumors than control in ESCC and melanoma mouse model." (PMID 33735820, 2021). "Furthermore, we found that the thymocytes from B16 melanoma-bearing mice, which display severe thymus atrophy at late tumor stages, exhibited reduced Mysm1 and IRF2 expression but enhanced Sca1 expression, suggesting that tumors may downregulate Mysm1 and IRF2 for thymic T-cell elimination." (PMID 27277682, 2016). "Other microarray datasets studied in melanoma implicate IL-8, CXCL13, IRF1, IRF2 and IL-12 as possible prognostic markers." (PMID 24762633, 2014). "The present findings revealed that MDA-7/IL-24 treatment of melanoma cells activates phosphorylation of STAT3 and down-regulates interferon regulatory factor (IRF-1) whereas up-regulating IRF-2 expression, which reduces iNOS expression level." (PMID 22629368, 2012). "This direction of effect is consistent with a potential role for IRF2 as a potential activator in both individual and haplotype-based reporter assays, but inconsistent with the direction of the relatively weak eQTL for CASP8 in melanoma tumors." (PMID 41542517, 2026). "When the isogenic pair of human IRF2-positive and negative primary melanomas were injected into humanized NSG mice, the IRF2-deficient tumors grew more rapidly than their IRF2-positive counterparts." (PMID 39281881, 2024).
melanoma (continued). "Interestingly, we observed significant downregulation of the IRF transcription factor family members (IRF1, IRF2, IRF5, IRF8) corresponding to attenuated interferon signaling in TRIM28HIGH melanomas, probably as a consequence of low immune cell infiltration." (PMID 33076560, 2020). "Using fine needle aspirates from 25 patients who were under standard treatment for melanoma (including IFN-α), they performed gene analysis and saw that markers of an active T cell response, such as IRF1, IRF2 and TLA-1, were present in lesions that responded to treatment." (PMID 24762633, 2014). "Whether the IRF2 effects on the human melanoma growth contribute to CPI resistance to in our system is not resolved by our data, although other rapidly growing tumors like B16 do respond to CPI." (PMID 39281881, 2024). "In our study, DMF reversed melanoma resistance to NKmK, reducing MHC II expression without affecting upstream IFNγ targets (USF1, IRF1, IRF2)." (PMID 41078003, 2025). "In fact, a recent study found that prior treatment with pegylated-IFN-alfa-2b increased the effectiveness of adjuvant pembrolizumab (anti-PD-1 treatment) in patients with surgically removable advanced melanoma, although IRF1 and IRF2 status was not evaluated." (PMID 39354629, 2024).
viral infection (11 papers, 2011 to 2025). "Various irfs (e.g., irf1, irf2, irf3, irf4b, irf7, irf9, and irf10) were previously found upregulated with poly(I:C) or viral infection in teleost species." (PMID 39211041, 2024). "A primate-specific lncRNA CHROMR can restrict viral infection of macrophages by sequestering the IFN regulatory factor (IRF)-2-dependent transcriptional corepressor IRF2BP2, thereby promoting the transcription of the ISG network." (PMID 37108410, 2023). "IFN and PKR had been reported to be upregulated in response to GCRV infection, which suggested that IFN-transcriptional inhibitor IRF2 shouldn't be over-expressed during viral infection." (PMID 29069722, 2017). "IRF1 and IRF2 of the IRF family of transcription factors play distinct roles in cellular response to viral infection." (PMID 25960866, 2015). "This strategy relies on IFNαβ-induced IRF2 to regulate critical cell differentiation decisions following viral infection of B cells." (PMID 22114555, 2011). "IRF-2 plays a role in viral infection through the IFNs signalling regulation." (PMID 37019881, 2023). "Notably, upon virus infection, also IRF2 was induced, both at mRNA and protein level." (PMID 34685580, 2021). "IRF2 binds to TLR3 and other IFN-inducible gene promoters and maintains an active chromatin structure in the unstimulated state, which is required for their induction, while IRF1 binding to these promoters activates their transcription upon viral infection." (PMID 25960866, 2015). "Once virus infection has been cleared, the IFNαβ-induced transcriptional repressor IRF2 exerts a negative feedback role to terminate IFNαβ expression and prevent inflammatory pathology." (PMID 22114555, 2011). "Expression of CHROMR is crucial for restricting viral infections in macrophages, and CHROMR can license IRF-dependent signaling and transcription of the ISGs network by sequestering the interferon regulatory factor (IRF)-2-dependent transcriptional corepressor IRF2BP2." (PMID 40285022, 2025). "Furthermore, viral infection significantly downregulated the expression of bta-miR-222, which was identified to increase IFN-I expression and suppress CPIV3 replication by directly targeting interferon regulatory factor 2 (IRF2)." (PMID 35746759, 2022).
gastric cancer (10 papers, 2017 to 2022). A primary or metastatic malignant neoplasm involving the stomach. "Interferon regulatory factor 2 (IRF-2) acts as an anti-oncogene in gastric cancer (GC); however, the underlying mechanism remains unknown." (PMID 35115027, 2022). "Interferon regulatory factor 2 inhibits gastric cancer invasion and migration by downregulating MMP1." (PMID 34445346, 2021). "While the role of IRF2 has not been established in cSCC, IRF2 has been identified as a tumor suppressor in lung cancer and gastric cancer and, paradoxically, as an oncogene in testicular embryonal carcinoma." (PMID 36009366, 2022). "It has been reported that IRF2 inhibits cell proliferation by inducing CLDN7 upregulation in oral squamous cell carcinoma, and inhibits cancer proliferation by promoting AMER-1 transcription in human gastric cancer." (PMID 36341357, 2022). "For instance, IRF2 expression detected by immunohistochemistry was significantly downregulated in gastric cancer (GC) tissues compared to the nontumor tissues." (PMID 30876449, 2019). "In gastric cancer (GC), TGF-β was shown to up-regulate miR-577 expression, which in turn targets SDPR, leading to EMT induction; and miR-520c, which was up-regulated in both cell lines and tissues and shown to increase proliferation, migration and invasion of cancer cells through IRF2 targeting." (PMID 31906022, 2019).
acute myeloid leukemia (9 papers, 2017 to 2023). Acute myeloid leukemia (AML) is a group of neoplasms arising from precursor cells committed to the myeloid cell-line differentiation. "miR-485-5p participated in the mediation of acute myeloid leukemia by targeting interferon-regulatory factor 2 (IRF2)." (PMID 34594577, 2021). "The present study focused on the miRNA/IRF2 axis in regulating Th1/Th2 ratio and cell apoptosis in acute myeloid leukemia (AML)." (PMID 37621743, 2023). "For example, miR222-3p, which is highly expressed in BMMSC-EVs, suppresses acute myeloid leukemia (AML) cell proliferation and promotes apoptosis by targeting the IRF2/INPP4B signaling pathway." (PMID 37242693, 2023). "IRF2 could attenuated apoptosis through induction of autophagy in acute myelocytic leukemia cells." (PMID 35012444, 2022). "The present study aimed to investigate the underlying role of interferon-regulatory factor 2 (IRF2)–inositol polyphosphate-4-phosphatase, type-II (INPP4B) axis in the regulation of autophagy in acute myeloid leukemia (AML) cells." (PMID 30876449, 2019). "In acute myeloid leukemia (AML), BM-MSC-derived miR-222-3p within sEVs induced the downregulation of IRF2/INPP4B signaling and increased apoptosis of the AML cell line THP-1." (PMID 37762393, 2023). "miR222-3p is highly expressed in BMSC-derived exosomes, which is delivered to negatively regulate the IRF2/INPP4B signaling pathway, thus, inhibiting proliferation and promoting apoptosis in acute myeloid leukemia (AML) cells by targeting IRF2." (PMID 36338118, 2022).
breast carcinoma (9 papers, 2017 to 2026). "IRF2 is reported to be an important regulator of breast cancer invasion and metastasis; however, its role in the antiviral process and immune regulation needs to be explored in further studies." (PMID 34092256, 2021). "In accordance with the gene expression levels, the protein levels of ZDHHC9, PCMT1, TMEM70 were significantly higher in breast cancer, and the protein levels of IRF2, KCNJ11 were higher in normal tissues." (PMID 34956313, 2021). "They identified that the development of IRF-2 expression was correlated with oncogenic activation in breast cancer." (PMID 28465494, 2017). "Interferon regulatory factor 1 (IRF-1) and IRF-2 expression in breast cancer tissue microarrays." (PMID 33537063, 2020). "For instance, the expression of IRF2 has been found to be related to breast cancer, and it has been reported that HMGB2 directly and significantly promotes breast cancer progression." (PMID 33537063, 2020). "EGR and NFkB and SP1 in breast cancer have been reported to induce the mRNA expression of IFNGR, while AP2 in breast cancer and IRF2-mediated negative feedback in esophageal cancer have suppressive roles." (PMID 37275859, 2023).
esophageal cancer (8 papers, 2011 to 2025). A primary or metastatic malignant neoplasm involving the esophagus. "Conversely, elevated expression of IRF-2 (an inhibitor of IRF-1 transcriptional activity) and high IRF-2/IRF-1 ratios were observed to be associated with worse prognosis in esophageal cancer." (PMID 21875439, 2011). "Notably, a study focusing on esophageal cancer cells revealed that the expression of IRF-2 was significantly upregulated in response to low concentrations of IFN-γ, contributing to the pathogenesis of esophageal cancer." (PMID 40909948, 2025). "In addition, overexpression of IRF2 promotes esophageal cancer cell proliferation and mutations of SNPs in genes such as IRF3, IRF5, and IRF7 may facilitate the progress of esophageal cancers, while IRF4 may be regarded as a protective factor in ESCC." (PMID 39384770, 2024). "miR-302b suppresses tumor growth and transcription factors protein expression through targeting erb-b2 receptor tyrosine kinase 4 (ERBB4), interferon regulatory factor 2 (IRF2), and Cxc chemokin receptor 4 (CXCR4) in esophageal cancer." (PMID 33729388, 2021).
pancreatic cancer (8 papers, 2017 to 2024). "It was reported that IRF2 gene was associated with several diseases in chickens like necrotic enteritis, pancreatic cancer, and atopic dermatitis and eczema herpeticum." (PMID 32677890, 2020). "IRF-2 has been reported to be up-regulated in pancreatic cancer, in which it is associated with tumor size and differentiation, tumor node metastasis stage, and survival." (PMID 29599126, 2018). "IRF2, which is overexpressed in pancreatic cancer and oesophageal squamous cell carcinoma, acts as an oncogene." (PMID 35620407, 2022). "The overexpression of IRF2 increased the expressions of cyclin D1, consequently reduced apoptosis and contributed to cell growth in pancreatic cancer." (PMID 33735820, 2021). "IRF2 is upregulated in pancreatic cancer and HCC cells, and high levels of IRF2 are associated with a worse feature of tumor infiltration depth." (PMID 33735820, 2021). "Whereas IRF-1 expression is reduced in pancreatic cancer specimens compared with adjacent normal tissues, IRF-2 gene expression is up-regulated." (PMID 29599126, 2018). "The involvement of IRF-1 and IRF-2 in the progression of human pancreatic cancer has also been reported." (PMID 29599126, 2018). "In addition, forced expression of IRF2 increased the expressions of proliferation-related genes cyclin D1 and proliferating cell nuclear antigen (PCNA), suggesting that IRF2 exerted oncogenic activities in human pancreatic cancer." (PMID 30876449, 2019). "Consistent with this, it has been proposed that increasing the IRF-1/IRF-2 ratio may serve as a novel therapeutic strategy for pancreatic cancer." (PMID 29599126, 2018). "Moreover, IRF-2 has been found to modulate the growth of pancreatic cancer cells by regulating proliferation and apoptosis effectors, such as cyclin D1 and BAX." (PMID 28465494, 2017). "Subsequent research using an in vitro model of pancreatic cancer has confirmed these clinical observations and thus, the tumor-suppressing and -promoting potentials of IRF-1 and IRF-2, respectively." (PMID 29599126, 2018).
COVID-19 (7 papers, 2021 to 2025). A disease caused by infection with severe acute respiratory syndrome coronavirus 2. "Individual genes associated with the COVID-19/sepsis shared hypermethylated and hypomethylated CpG genes include type I IFN-related genes, like IRF2, and others, such as IL1A and CCR2, that are involved in inflammatory processes and monocyte chemotaxis, respectively." (PMID 36443794, 2022). "Instead, IRF2 is a member of the interferon regulatory transcription factor (IRF) family, and its enhanced activity has been reported in neutrophils from COVID-19 patients." (PMID 39811276, 2025). "The third module set was enriched for classical (C2H2) zinc finger (ZNF) genes and contained IRF2 and IL16; expression of these eigengenes was lower in COVID-19 and influenza compared with healthy volunteers and sepsis cases." (PMID 35216673, 2022). "Thus, the upregulation of IRF2, IRF7, and STAT, in all cell types may be driving the amplification of IFN response pathways and thereby the overproduction of inflammatory cytokines that contribute to COVID-19 CRS pathogenesis." (PMID 34163359, 2021). "TF activity analysis indicated a robust regulation by IRF2/IRF9 and STAT1/2 for this cluster of cells, within both severe and non-severe COVID-19." (PMID 34721400, 2021).
lung cancer (6 papers, 2017 to 2025). A malignant neoplasm involving the lung. "For example, miR-181a overexpression facilitated proliferation, migration, autophagy, and decreased apoptosis by suppressing interferon regulatory factor 2 (IRF2) expression in lung cancer." (PMID 29588850, 2018). "For example, IRF2 could suppress cell proliferation and migration ability and promote cell apoptosis in nonsmall cell lung cancer cells." (PMID 36199790, 2022). "However, IRF2 inhibition by miR-450 suppresses lung cancer cells’ progress." (PMID 39384770, 2024). "The detailed functions of IRF2, IRF4, and IRF8 in lung cancer are complex and controversial." (PMID 39384770, 2024).
psoriasis (6 papers, 2014 to 2025). An autoimmune condition characterized by red, well-delineated plaques with silvery scales that are usually on the extensor surfaces and scalp. "IRF2 has been broadly associated with inflammatory diseases of the skin including psoriasis, but the relative contributions of epithelial and immune cells are difficult to discern with IRF2 KO models." (PMID 31611556, 2019). "Irf2 deficient mice developed an inflammatory skin disease similar to psoriasis, which was thought to be attributable to enhanced type I IFN signaling." (PMID 25285625, 2014). "Notably, IRF2 belongs to the PSORS3 Psoriasis Susceptibility locus on the 4q25 chromosome as identified through genetic linkage studies." (PMID 36833372, 2023). "Moreover, IRF2-deficient mice spontaneously display an inflammatory skin disease similar to human psoriasis because CD8+ T cells from IRF2-deficient mice show hyper-responsiveness to type I IFNs." (PMID 32456211, 2020). "IRF-2+/- mice (a haploinsufficiency model) showed more severe psoriasis-like dermatitis compared with wildtype mice." (PMID 34790055, 2021). "In psoriasis, IRF2 is known to be involved in pathogenesis, while studies on other IRFs are limited." (PMID 32456211, 2020). "Imiquimod-induced psoriasis-like skin inflammation was severer in IRF-2 hetero-knockout mice than in wild-type mice." (PMID 32456211, 2020). "Individual roles of IRF2BP2, as well as its interaction with IRF2 in the IRF2/IRF2BP2 repression complex, have been described in autoimmune diseases, including asthma, multiple sclerosis, atopic dermatitis, and psoriasis, where CHROMR has been implicated." (PMID 40559622, 2025). "After that, genetically, the variation at the IRF2 gene but not IRF1 gene was found to be associated with susceptibility to psoriasis." (PMID 32456211, 2020). "IRF2 knockout mice show hyper-responsiveness to type I IFN signaling and exhibit lesions resembling human psoriasis." (PMID 34790055, 2021). "Concerning psoriasis, IRF1 and IRF2 are the most studied IRFs." (PMID 32456211, 2020).